NLRP3 (NLR family pyrin domain containing 3)
Diseases named in the same sentence as NLRP3 in open-access papers (continued):
Sharing a sentence is not in itself a finding about the gene and the disease.
diabetes (continued). "Besides the beneficial effects of phytochemicals targeting NLRP3 signaling on liver and kidney inflammation associated with diabetes, a recent study has shown that the isoflavone formononetin alleviated cognitive dysfunctions associated with diabetes via NLRP3 inhibition." (PMID 31200447, 2019). "In conclusion, our study demonstrates that topical application of rTMD1 enhances corneal wound healing in diabetes by inhibiting HMGB1/TLR4/NLRP3/IL‐1β–mediated inflammation." (PMID 41503166, 2026). "According to recent studies, chronic systemic inflammation mediated by activation of the inflammasome NOD-like receptor protein 3 (NLRP3) is a key factor in the pathophysiology of type 2 diabetes mellitus (DM)." (PMID 41640166, 2026). "HMGB1 is a typical DAMP that engages TLR4 to activate NF‐κB and prime the NLRP3 inflammasome, thereby amplifying IL‐1β–driven inflammation; diabetes‐related AGEs and ROS further potentiate NLRP3 activation and pyroptosis, delaying epithelial repair." (PMID 41503166, 2026). "Pharmacological inhibition of sEH attenuated diabetes-induced mitochondrial damage, mitochondrial reactive oxygen species (mtROS) production, NLRP3 inflammasome activation, and renal dysfunction both in vivo and in vitro." (PMID 42131331, 2026). "In diabetes-affected hearts, NLRP3 activation in cardiomyocytes and infiltrating macrophages enlarges infarct size and accelerates maladaptive ventricular remodeling." (PMID 41488670, 2025). "The NLRP3 inflammasome can act both as a sensor and contributor in the pathogenesis of obesity, certain types of cancer, metabolic diseases such as diabetes, atherosclerosis, cardiovascular diseases, and neurodegenerative diseases." (PMID 40761804, 2025). "NETs in the setting of diabetes can also function as a stimulus for NLR family pyrin domain-containing 3 (NLRP3) inflammasome activation in macrophages to promote IL-1β-dependent exacerbation of inflammation." (PMID 39875729, 2025). "The clinically most advanced NLRP3 inhibitor is dapansutrile, which is currently being tested in a 6 month trial of diabetes and related complications (ClinicalTrials.gov NCT06047262)." (PMID 39496966, 2025). "For instance, LncRNAs have been shown to exacerbate hepatitis C virus (HCV)-Induced Type 2 diabetes mellitus (T2DM) through the miRNA-223-3p/NLRP3 molecular axis." (PMID 41011417, 2025). "In summary, these findings demonstrate that diabetes promotes activation of the NLRP3 inflammasome–CASP1–galectin-3 axis within atrial tissue, contributing to the initiation of atrial fibrillation." (PMID 40649732, 2025). "Metabolic conditions such as obesity and diabetes can activate the NLRP3 inflammasome and other inflammatory cytokines in atrial myocytes, contributing to atrial remodeling and AF promotion." (PMID 39888955, 2025). "A model of STZ-induced diabetes was shown to be characterized by high serum concentrations of IL1β and renal levels of NFκB p65, NLRP3, TXNIP, and MDA, but low levels of IL10 and TAC and Nrf2 gene expression." (PMID 41020857, 2025). "The findings presented herein extend these prior studies and demonstrate that REDD1 expression in podocytes is required for NF-κB-dependent NLRP3 inflammasome activation and subsequent induction of pyroptosis in experimental models of diabetes." (PMID 39920111, 2025). "This dual pro-inflammatory and pro-tumorigenic role positions NLRP3 as a critical molecular node connecting the chronic inflammatory environment of diabetes with tumorigenesis in HNSCC." (PMID 40881172, 2025). "In contrast, SGLT2 inhibitors—now widely adopted in cardiovascular medicine—demonstrate favorable effects on NLRP3 suppression, atrial structural remodeling, and arrhythmia prevention, particularly in patients with diabetes or heart failure." (PMID 40649732, 2025). "Novel therapeutic strategies, including targeting the NLRP3–IL-1β axis, aim to curb this inflammatory burden and potentially slow the progression of diabetes-related vascular disease." (PMID 40149704, 2025).
diabetes (continued). "It is well-established that patients with diabetes often present with elevated uric acid levels, and recent studies highlight a mechanistic link between hyperuricemia and inflammation via NLRP3 inflammasome activation." (PMID 40648980, 2025). "Increased expression of the NEK7 gene has been reported in patients with gestational diabetes, and suppression of NLRP3 inflammasome activation related to NEK7 overexpression has been shown to mitigate diabetes-induced muscle atrophy." (PMID 41465472, 2025). "Chronic inflammation plays a pivotal factor in the development of diabetes, accompanied by elevated levels of NLRP3 inflammasome and other inflammatory factors." (PMID 41264598, 2025). "Vildagliptin is superior to linagliptin in ameliorating diabetes-induced lung injury primarily via targeting the NLRP3 inflammasome pathway." (PMID 40562805, 2025). "AIM2 activation in macrophages also promotes necrotic core expansion and plaque instability—particularly in diabetes and clonal hematopoiesis—highlighting convergent DNA-sensing routes that intersect with NLRP3 biology and innate immune training." (PMID 41488670, 2025). "The involvement of the NLRP3 inflammasome in the pathophysiology of diabetes remains a subject of considerable scientific contention, with experimental and clinical evidence yielding divergent interpretations." (PMID 40943351, 2025). "Previous studies have shown that factors such as hypertension, diabetes and infections can induce stress in kidney cells, leading to NLRP3 activation." (PMID 40079088, 2025). "The shared pathways between neuroinflammation and diabetes mellitus involve the NLRP3 inflammasome and subsequent production of the IL-1β." (PMID 40771585, 2025). "Second, they inhibit inflammasome activation (e.g., NLRP3) by reducing oxidative stress and mitochondrial dysfunction, critical drivers of neuronal damage in diabetes." (PMID 40948877, 2025). "Chronic low-grade inflammation in obesity and type 2 diabetes mellitus activates the NLRP3 inflammasome via metabolic stressors, leading to insulin resistance." (PMID 40307577, 2025). "Hypoglycaemic agent’s oral administration in neuroinflammation The NLRP3 inflammasome and its consequent generations of IL −1 β are involved in thein the common pathways between neuroinflammation and diabetes." (PMID 40771585, 2025). "Effects of silver nanoparticle‐loaded 18β‐glycyrrhetinic acid on P2X7 receptor and endoplasmic reticulum stress‐mediated NLRP3 inflammasome activation in testicular tissue in an experimental diabetes model in rats." (PMID 41280745, 2025). "In diabetes, the body recognizes the abnormal elevated free fatty acids, the sustained hyperglycemic levels and ROS as DAMPs, compelling the trigger of NLRP3 inflammasome activation." (PMID 40943351, 2025). "In endocrine diseases, hyperglycemia induces apoptosis and pyroptosis of hippocampal neurons via an NLRP3-dependent pathway, which is associated with depression-like symptoms in STZ-induced diabetes models." (PMID 40936908, 2025). "Tripdiolide treatment significantly decreased TLR4 by 45.3%, P-NF-κB by 54.9%, and NLRP3 by 30.7% in the kidney of diabetes mice (p < 0.05)." (PMID 40176887, 2025). "Compared with Ctrl mice, the expression of TLR4, P-NF-κB and NLRP3 in the kidney of diabetes mice were markedly escalated (p < 0.01)." (PMID 40176887, 2025). "In our study, a high-fat diet induced the activation of the NLRP3 inflammasome in hepatocytes, triggering cell pyroptosis, releasing inflammatory cytokines, and contributing to the pathogenesis of diabetes-related liver fat deposition." (PMID 40136402, 2025). "In the present study, we aimed to determine the effects of AgNP+18β‐GA application, which has a strong antioxidant effect, on P2X7 receptor and endoplasmic reticulum stress‐mediated NLRP3 inflammasome activation in diabetes‐induced testicular tissue." (PMID 41280745, 2025).
diabetes (continued). "Ultimately, the convergence of these factors—NLRP3 activation, proinflammatory adipokines, AGE–RAGE interactions, and endothelial dysfunction—explains why individuals with diabetes face an enhanced atherosclerotic risk." (PMID 40149704, 2025). "We are currently investigatingthe role of hyperglycemia in NLRP3 inflammasome activation and programmedcell death in the diabetic retina." (PMID 40758602, 2025). "The Nod-like receptor protein 3 (NLRP3) inflammasome is involved in several diseases, including diabetes, atherosclerosis, Alzheimer’s disease, inflammatory bowel disease, and multiple sclerosis." (PMID 40002330, 2025). "The NLRP3 inflammasome is a key driver of chronic inflammation and metabolic disturbances in diabetes, contributing to IR, β-cell damage, and related complications." (PMID 40429855, 2025). "Studies have demonstrated that silencing NLRP3 can inhibit pyroptosis in H9c2 cardiomyocytes exposed to high-glucose conditions and ameliorate cardiac pyroptosis, inflammation, and fibrosis in Type 2 diabetes mellitus (T2DM) rats." (PMID 40242439, 2025). "Our results show for the first time that DAPA plays an important role in the treatment of diabetes-related liver fat deposition by targeting NLRP3-Caspase-1 axis-mediated cell pyroptosis." (PMID 40136402, 2025). "Early studies have shown that Nlrp3 is involved in driving inflammation and renal damage in diabetes models." (PMID 40959205, 2025). "TRPC6 knockout in type 2 diabetes mellitus induced hepatic inflammation and fibrosis, inhibited calcium overload, and suppressed the calcineurin/nuclear factor of activated T cells 2/NLRP3 signaling pathway in mice." (PMID 41450741, 2025). "To date, the role of NLRP3 in MetS including obesity, diabetes, dyslipidemia, hypertension and AS is well studied." (PMID 40433411, 2025). "In diabetes, persistent hyperglycemia and metabolic dysregulation lead to chronic NLRP3 activation in pancreatic β-cells, adipose tissue, and vasculature." (PMID 41296433, 2025). "Conversely, NLRP3 plays a greater role in metabolic or acute inflammasome-driven tissue injury, particularly in diabetes mellitus and its complications." (PMID 40943351, 2025). "In metabolic diseases such as obesity and diabetes, systemic priming of the inflammasome is accompanied by myocardial oxidative stress and mitochondrial dysfunction—key triggers for NLRP3 activation and arrhythmic vulnerability." (PMID 40649732, 2025). "Previous work has shown that BMP2 inhibits NLRP3 inflammasome activation during the development of type 2 diabetes mellitus-induced cardiomyocyte injury." (PMID 39334820, 2024). "On the other hand, it was reported that in diabetes, the body produces a large amount of ROS, inducing the formation of NLRP3 inflammatory bodies." (PMID 38472840, 2024). "NLRP3 is ubiquitously expressed in urothelia and can be activated by metabolites commonly found in urine of patients with diabetes." (PMID 38682210, 2024). "To explore the critical role of NLRP3 in diabetes-induced senescence of the vascular smooth muscle layer, we inhibited NLRP3 in diabetic mice and VSMCs through MCC950 treatment." (PMID 38733164, 2024). "ADAM17 plays a direct role in the pathogenesis of diabetes-associated neurodegenerative processes, including the cell signaling pathways involving both diseases, such as AKT, NF-κB, JAK-STAT, MAPK, and NLRP3 inflammasome pathways." (PMID 38963109, 2024). "It has been recently revealed that thioredoxin-interacting protein (TXNIP), a key element of diabetes progression, activates the NLRP3 inflammasome and subsequent pancreatic B-cell pyroptosis in diabetic mice." (PMID 38248345, 2024). "A recent study reported that NLRP3 over expression contributes to diabetes related disorders, including atherosclerosis, diabetic nephropathy, and cardiomyopathy." (PMID 38637900, 2024). "Pharmacological inhibition on NLRP3/caspase 1/GSDMD cascade by empagliflozin was shown to be beneficial against pancreatic damage during diabetes." (PMID 39253076, 2024).
diabetes (continued). "NLRP3 inflammasome pathway is involved in diabetes development due to its influence on glucose tolerance, insulin resistance, inflammation, and apoptosis mediated in adipose tissue." (PMID 38963109, 2024). "AR/PCC alleviated diabetes-related osteoporosis by upregulating the antioxidant response protein (Nrf2) to reduce the activation of the NLRP3-mediated canonical pyroptosis pathway in vertebral osteoblasts." (PMID 38895114, 2024). "Basic studies have shown that microglial NLRP3 inflammasome activation mediates diabetes-induced depression-like behavior by triggering neuroinflammation." (PMID 38326834, 2024). "Dysregulation of NLRP3 inflammasome activation, specifically chronic activation of NLRP3 inflammasome, has been involved in pathogenesis of rheumatoid arthritis, gouty arthritis, diabetes and worsening disease conditions." (PMID 38644450, 2024). "Previous studies have shown that AMPK activation can reduce NLRP3 inflammasomes in a variety of diseases, such as diabetes and ischemic stroke." (PMID 39545058, 2024). "In the development of diabetes and its complications, the NLRP3 inflammasome plays an important role." (PMID 38560269, 2024). "A key player in the intersection of diabetes mellitus and inflammatory bowel disease is the NLRP3 inflammasome, which regulates the production of pro-inflammatory cytokines leading to prolonged inflammation and tissue damage." (PMID 39328924, 2024). "In diabetes, hyperglycemia can stimulate the activation of NLRP3, thus activate Caspase-1, which can promote the maturation of cytokines pro-IL-1β and pro-IL-18 to release the cleaved fragments of active IL-1β and IL-18, and lead to pyroptosis." (PMID 39545058, 2024). "It has been reported that miR-9-5p can mitigate diabetes by downregulating pyroptosis, which is coupled with reductions in IL-1β, IL-18, NLRP3, and Caspase-1." (PMID 38934781, 2024). "In particular, the activation of the NLR family pyrin domain-containing 3 (NLRP3) inflammasome has been involved in several age-related conditions, including type 2 diabetes mellitus and Alzheimer’s disease (AD)." (PMID 39000412, 2024). "To investigate the effect of FGF21 on NLRP3 inflammasome activation induced by diabetes, we assessed the extent of NLRP3 inflammasome activation in the aortas of diabetic mice and smooth muscle cells." (PMID 38733164, 2024). "High expression of NLRP-3, caspase-1, IL-1β and IL-18 was observed in macrophages isolated from wounds of patients with type 2 diabetes mellitus whose wounds lasted for at least 3 months." (PMID 38957662, 2024). "HECTD3 promotes NLRP3 inflammasome and pyroptosis, thereby exacerbating diabetes-related cognitive impairment by stabilizing MALT1 and regulating the JNK pathway." (PMID 38384936, 2024). "This review provides substantial evidence supporting the exacerbation of prevalent lifestyle diseases, such as obesity, diabetes, chronic respiratory diseases, oral diseases, and cardiovascular diseases, by the NLRP3 inflammasome." (PMID 38945951, 2024). "Studies have shown that NLRP3 inflammasome deletion significantly reduces diabetes‐induced depressive phenotypes." (PMID 38752512, 2024). "In fact, release of particles in rheumatoid arthritis (pentaxin 3 and its ligand C1q), gout (uric acid crystals), and diabetes significantly over-activates NLRP3 inflammasome, which contributes in development of these peripheral inflammatory diseases." (PMID 38644450, 2024). "A study showed that patients with periodontitis and periodontitis and diabetes exhibited high serum and salivary NLRP3 inflammasome levels compared to diabetes patients and healthy subjects." (PMID 38954692, 2024). "Aberrant expression of NLRP3 contributes to multiple inflammatory disorders, including obesity, diabetes, dyslipidemia, hypertension, traumatic brain injury, and cerebrovascular disease." (PMID 38637900, 2024).
diabetes (continued). "In individuals with diabetes, there was a statistically significant increase in the levels of NLRP3, ASC, and subsequent proinflammatory factors." (PMID 38248345, 2024). "Here, we for the first time observed that NET degradation improved the erectile function of diabetic ED rats and inhibited NLRP3-mediated pyroptosis in the rat cavernosum tissues." (PMID 39014129, 2024). "Reviews mainly discussed heart failure, metabolic syndrome, pancreatitis, and DR, and also addressed the involvement of the NLRP3 inflammasome protein in diabetes regulation." (PMID 38510357, 2024). "Studies haveshown that the inflammatory response is present inthe onset and progression of diabetes, and disturbedglucose metabolism in diabetic patients promotes thesynthesis of NLRP3 inflammatory vesicles, creating achronic inflammatory response." (PMID 39876912, 2024). "Sustained NLRP3 inflammasome activation with infiltration of neutrophils was reported in diabetes, in line with the observation that BI-1–/– mice presented more MPO-positive cells in pancreatic sections that were corrected with IRE1α RNase inhibition." (PMID 38744890, 2024). "Several promising studies have discussed the impact of NLRP3 inflammasome and NF-κB signaling in propelling the inflammatory cascade, glomerular damage, and fibrotic changes in diabetic kidneys." (PMID 37237918, 2023). "Collectively, teneligliptin mitigated diabetes-related CI by repressing the ER stress and NLRP3 inflammasome in diabetic mice." (PMID 38127000, 2023). "This review will present the mechanisms of NLRP3 activation and its importance for the initiation of type 1 diabetes mellitus (T1D), T2D, and the subsequent chronic complications that arise." (PMID 37762961, 2023). "In this context, a better understanding of the activation of NLRP3 inflammasome in diabetes mellitus with COVID-19 will facilitate further research and better treatment of diabetes mellitus with COVID-19." (PMID 37868953, 2023). "In terms of the NLRP3 inflammasome’s role in inflammatory diseases, rheumatoid arthritis, diabetes, cancer and neurodegenerative diseases are just a few to mention." (PMID 36831081, 2023). "Pathways commonly activated by diabetes-related conditions include NF-κB, NLRP3 inflammasome, fractalkine/CX3CR1, MAPKs, AGEs/RAGE and Akt/mTOR." (PMID 36869375, 2023). "Tranilast binds directly to the NACHT structural domain of NLRP3 and inhibits the assembly of NLRP3 inflammasome, showing therapeutic effects in gouty arthritis and type 2 diabetes mellitus mouse models." (PMID 37426634, 2023). "Aerobic exercise-induced amelioration of diabetes-induced inflammation in the prefrontal cortex by inhibiting FOXO1/NF-κB/NLRP3 inflammatory signaling pathway." (PMID 37859981, 2023). "In conclusion, teneligliptin alleviated diabetes-related CI by repressing the ER stress and NLRP3 inflammasome in diabetic mice." (PMID 38127000, 2023). "Several studies have indicated that the VDUP1/NOD-like receptor family protein 3 (NLRP3) pathway contributes to the development of diabetes, cardiovascular diseases, and Alzheimer’s disease." (PMID 37686390, 2023). "Diabetes as a stimulus was of interest in this context because many publications report NLRP3 inflammasome activity in podocytes in the context of hyperglycemia and diabetes." (PMID 37744356, 2023). "This attenuated diabetes is due in part to NLRP3-/- APC having a decreased capacity to promote Th1 cell differentiation; Th17 cell differentiation, however, is unaffected." (PMID 37081890, 2023). "Several studies have suggested that the activation of the NLRP3 inflammasome plays a role in the development of insulin resistance in T2D and high fat diet-induced diabetes." (PMID 37240345, 2023). "Of note, AR and PCC have been documented to ameliorate inflammatory responses in a variety of diabetic complications, such as diabetic nephropathy and diabetes‐induced cognitive impairment, through the reduction in Nlrp3 and Caspase1 levels." (PMID 37621124, 2023).